CD4 (CD4 molecule)
Diseases named in the same sentence as CD4 in open-access papers (continued):
Sharing a sentence is not in itself a finding about the gene and the disease.
co-infection (continued). "Age, depression, comorbidity, HCV co-infection, current substance use, CD4 count, or HIV viral load were predictive of antibody level." (PMID 42041389, 2026). "To replicate this experiment using HostSim, we represent HIV-1 co-infection as a linear decline of CD4+ T-cells calibrated to T-cell blood concentrations reported from the 1990s71,72 measured prior to any treatment studies." (PMID 41542609, 2026). "A meta-analysis from Ethiopia also found a significant association among low CD4 counts, advanced HIV stage as per WHO guidelines and HIV-TB co-infection." (PMID 40771827, 2025). "In our study, patients with co-infections tended to have a higher proportion of CD4+CD8+ DP T cells." (PMID 40416960, 2025). "Our theoretical modelling suggests that co-infection with TIP-2 of productively infected CD4+ T cells leads to partial inhibition of produced infectious virions." (PMID 41157648, 2025). "Individuals with HIV/HBV coinfection experienced an annual rise of 65.9 cells/μL in CD4 cell counts." (PMID 40046188, 2025). "Despite elevated baseline CD4+ counts, co-infection with HIV-1 and HTLV-1 has been demonstrated to exacerbate a number of complications, including neurological complications, opportunistic infections, and mortality rates." (PMID 40284988, 2025). "Increased CX3CR1 expression on CD4+ and CD8+ T cells in PLWH has been associated with CMV co-infection, with an enrichment of CMV-specific populations, some of which target the vascular endothelium." (PMID 40920867, 2025). "Higher immunosuppression in people living with HIV possibly leads to increased vulnerability to TB infection, or co-infection with TB leads to further decrease in immunity and CD4 counts in HIV positives." (PMID 40771827, 2025). "This prospective study highlights the significance of quantitative HBsAg and CD4 cell counts in people living with HIV/HBV coinfection." (PMID 40046188, 2025). "Prevalence of HIV coinfection was 69.8% (173/248) with a median CD4 cell count of 102 cells/mm3 (interquartile range [IQR]: 33.5–240) and 23.7% (41/173) virological suppression." (PMID 40342012, 2025). "The median and mean curves go mostly above the deterministic solution, which indicates that the deterministic model underestimates productive co-infection of CD4+ T cell." (PMID 41157648, 2025). "The most significant alteration in HIV-Mtb co-infection was the near complete loss of MHC class II interactions, replaced by MHC class I engagement, particularly evident in CD4+ TEM cells." (PMID 41394852, 2025). "Specifically, the co-infection group exhibited a marked reduction in CD4+ naïve T cell (P < 0.01) and Th2 cell frequencies (P < 0.05) relative to HCs, while Th1 cell populations significantly expanded (P < 0.01)." (PMID 41394852, 2025). "Coinfection was nevertheless frequent, especially in HIV-positive patients with profound CD4 cell depletion, who showed a mean of two concomitant infections and an overall coinfection rate of 28%." (PMID 40558973, 2025). "Our study demonstrates that HIV-Mtb co-infection profoundly reshapes CD4+ T cells immunity by driving exhaustion and functional dysregulation." (PMID 41394852, 2025). "Research has shown that HIV infection results in the destruction of CD4+ T cells in the host’s immune system while impairing the quality of the hepatitis B virus (HBV)-specific T-cell response in the setting of HIV/HBV coinfection." (PMID 40046188, 2025). "It was observed that patients with HIV-TB co-infection had significantly lower CD4 counts than the HIV-only patients both at the baseline (χ2=27.345; P<0.001) and at 6 months follow-up (χ2=14.994; P=0.001)." (PMID 40771827, 2025). "Deep learning models, including convolutional neural networks, assist in diagnosing co‐infections like TB through chest X‐rays, while bidirectional recurrent neural networks capture temporal trends in VL and CD4 counts." (PMID 40990267, 2025).
co-infection (continued). "The aberrant MHC I engagement on CD4+ TEM cells underscore a co-infection-specific mechanism of T cell dysregulation." (PMID 41394852, 2025). "In the context of VL relapse, the CD4+ T-lymphocyte count is one of the most common parameters for predicting the clinical evolution of patients with VL/HIV co-infection." (PMID 40145085, 2025). "Coinfection, particularly in people with advanced HIV disease (eg, low CD4 cell counts), is associated with an increased risk for severe mpox disease, hospitalization, and mortality." (PMID 40498594, 2025). "In people living with co‐infection and low CD4 counts, HBV‐related immune restoration disease and hepatic flare can occur following initiation of ART." (PMID 40708534, 2025). "Patients with co-infections of HIV/HTLV-1 typically exhibit significantly elevated CD4+ T-cell counts in comparison to those with HIV-1 mono-infection." (PMID 40284988, 2025). "Integrating cellchat analysis, we found that co-infection induced significant plasticity in CD4+ T cell differentiation, shifting the terminal state from conventional Th1 dominance toward a Th1/Th17 hybrid phenotype." (PMID 41394852, 2025). "On the other hand, PLHIV with active TB co-infection exhibited the highest viral load and lowest CD4/CD8 ratio, confirming the expected advanced HIV disease progression reported earlier." (PMID 41148837, 2025). "In the univariable analysis, age, disease course, dyspnea, RPILD, AST, ESR, CRP, CD4+T cells, CD8+T cells, co-infection and treatments showed significant association with death(all p<0.05)." (PMID 41333459, 2025). "Despite the presence of sufficient levels of CD4+ cells, HIV-1/HTLV-1 co-infection has been demonstrated to be significantly associated with a shorter survival time." (PMID 40284988, 2025). "Previous studies have found a high prevalence of HIV and hepatitis C co-infection in the IDU cohort, as well as lower CD4-cell counts during co-infection." (PMID 39599831, 2024). "We and others have shown that HbTg co-infection results in decreased IFN©−producing CD4+ and CD8+ T cells." (PMID 38950025, 2024). "The low BMI reflects advanced HIV disease, lower CD4 counts, and a potentially increased likelihood of coinfections." (PMID 38251391, 2024). "For instance, two reported fatal cases with mpox and HIV co-infection had a CD4+ T-cells count < 200/μL." (PMID 38793665, 2024). "In the macaque model of co-infection, skewedpulmonary CD4+ TEM responses persist, and new TB lesions formdespite cART treatment." (PMID 39257997, 2024). "Previous studies based on smaller samples have shown that age, sex, coinfections with hepatitis C virus (HCV) and baseline CD4 + T cell count were risk factors for immunological non-response." (PMID 38287246, 2024). "In both groups with HIV/TB co-infection prevailed patients with severe immunosuppression: 76.6% and 66.7% CD4+T cell count < 200 cells/mm3 vs. 30.8% in group with HIV alone (p = 0.0250)." (PMID 38790916, 2024). "As the primary target of HIV infection, CD4+ T cells are severely affected during HIV/Mtb coinfection." (PMID 39204027, 2024). "HIV co-infection is another risk factor for PKDL development and its severity, especially in patients with low CD4+ counts." (PMID 39359727, 2024). "We show that HIV co-infection is the main driver in changing the memory distribution of HLA-E/Mtb specific CD4+ and CD8+ T cell subsets." (PMID 39790998, 2024). "In cases of HCV co-infection, there is a detrimental impact on the homeostasis of CD4+ T-cell counts, facilitating HIV replication and contributing to the persistence of viral reservoirs." (PMID 38392872, 2024). "In a recent study, a larger size of the HIV reservoir in resting CD4+ T cells was observed among individuals with HCV/HIV co-infection who were undergoing ART treatment." (PMID 38392872, 2024). "Compared to PTB, HIV co-infection, CD4+ T cell less than 550 /uL, and age less than 45 years were risk factors for TBM, and TBM was associated with higher mortality rates." (PMID 38767391, 2024).
co-infection (continued). "Tick-borne pathogen co-infection status showed positive effects on percent IL-10+ and PD-1+ CD4+ T cells, with posterior probabilities of being positive of 0.806 and 0.786, respectively." (PMID 38335163, 2024). "This is because HIV co-infection with Treponema pallidum has been associated with increased HIV viral load and decreased CD4 counts." (PMID 39321171, 2024). "TB co-infection has also been proposed as a potential factor that can affect the long-term chances of immune recovery through increased apoptosis of CD4+ T cells." (PMID 38699317, 2024). "Currently, according to the Infectious Disease Society of America (IDSA) guidelines, chronic maintenance therapy (secondary prophylaxis) is only indicated in case of HIV-coinfection and low CD4+ counts." (PMID 39359727, 2024). "This user-friendly tool incorporates key risk factors, including HBV/HCV co-infection, HIV RNA load, CD4+ T-cell count, and Neu and Lym levels, to provide personalized risk estimates." (PMID 38988810, 2024). "We observed that P. fragile co-infection resulted in parasitemia and anemia, as well as persistently detectable viral loads (VLs) and decreased absolute CD4+ T-cell counts despite daily ART treatment." (PMID 39066199, 2024). "It is well established that CD4+ cell counts are critical drivers of coinfection vulnerability and worsened outcomes in people living with HIV." (PMID 39065058, 2024). "HIV co-infection, CD4+/CD8+ T-cell counts less than 1, cranial nerve impairment, paralysis, cerebral infarction, PRO less than 450 mg/L, WBC less than 10 × 106 /L, and CL more than 120 mmol/L were risk factors for TBM cases with mixed intracranial infections." (PMID 38767391, 2024). "The depletion of Mtb-specific CD4+ T cells during HIV coinfection leaves behind less differentiated phenotypes with reduced motility." (PMID 39204027, 2024). "The Mann–Whitney test indicated that the level of peripheral blood CD4+ T lymphocytes in the HIV-MTB co-infection group was significantly lower than that in the MTB mono-infection group (Z = −6.07, p < 0.001)." (PMID 39205309, 2024). "We performed in-depth phenotyping on circulating HLA-E/Mtb specific and total T cells in individuals with various stages of TB infection and demonstrate that HIV co-infection is the main driver changing the distribution of CD4+ and CD8+ T cell memory subsets." (PMID 39790998, 2024). "In this study, CD4 T- and CD8 T-lymphocyte count, CD4/CD8 ratio, viral load, lymphocyte count, the neutrophil/lymphocyte and platelet/lymphocyte ratios in HIV-positive women were associated with HPV coinfection." (PMID 39699423, 2024). "Our findings of liver fibrosis progression being associated with lower nadir CD4+ T-cell count supports the importance of early and sustained suppressive HBV-active ART in reducing morbidity and mortality in PWH and HBV co-infection." (PMID 38518655, 2024). "Our previous studies have indicated that the baseline CD4+ T cells count and percentage before cART initiation are predictors of immune recovery in TB-negative children infected with HIV, with TB co-infection potentially causing a delay in immune recovery." (PMID 38699317, 2024). "Our model recapitulates this phenotype as is seen by >10% CD4+ TEM in BAL collected from the same RM during LTBI phase thatreduces to less than 3% post SIV co-infection." (PMID 39257997, 2024). "After adjusting for maternal HIV viral load, CD4 count and CMV co-infection, the risk of infant mortality doubled for each log rise in maternal CRP (aHR 2.09; 95% CI 1.33, 3.27)." (PMID 38632279, 2024). "In this study, we investigated the effect of H. pylori co-infection on CD4+ T cell count and HIV viral load dynamics in HIV-positive individuals in a high co-endemic setting." (PMID 38494500, 2024). "The following variables were selected for multivariable logistic regression analysis based on a P value threshold of less than 0.25: age, sex, CD4 level, BMI, TB-co-infection, duration on HAART, and viral hepatitis." (PMID 38605149, 2024).
co-infection (continued). "Kaplan–Meier curves showed significantly lower survival probabilities among TB/HIV co-infections with a low baseline CD4+T-lymphocyte count (χ2 = 8.439, P = .015)." (PMID 36749231, 2023). "In our study, we found good retention across all WHO clinical stages, TB/HIV co-infection status, and CD4 count." (PMID 38282767, 2023). "Key among these were medication adherence, baseline and therapeutic CD4 levels, the presence of co-infections, and the advanced clinical stage of the infection." (PMID 37884997, 2023). "Findings from similar studies conducted in Ethiopia revealed educational status, wealth index, migrations, drug dependency, WHO clinical stage, and baseline CD4 count as significant predictors of this TB/HIV co-infection." (PMID 36952538, 2023). "This assay is based on the co-infection of isolated CD4+ T-cells from HIV-seronegative donors with an HIV reporter construct and a virus expressing two antiapoptotic proteins (MCL1 and Bcl2)." (PMID 37874295, 2023). "Baseline CD4+ T cell counts, advanced age, co-infection with HCV, thymic dysfunction, immune activation, and genetic factors contribute to poor immune recovery." (PMID 37928477, 2023). "In our study, we found that HIV/HTLV-1 co-infected patients had a higher baseline CD4 cell count and, in the multivariate Cox regression analysis, that this co-infection significantly increased mortality, whilst ART use decreased mortality." (PMID 37513716, 2023). "Netherlandish and Sub-Saharan African studies showed that long-term TDF-containing ART led to a significant decrease in HBsAg in HBeAg-positive patients with HIV/HBV coinfection with high CD4 cell counts." (PMID 36844414, 2023). "Higher liver-related mortality was observed in HIV/HBV co-infection with lower CD4+ T cell counts than in HIV or HBV mono-infection." (PMID 37298575, 2023). "We expect coinfection to be mediated by the abundances and locations of both viruses and the CD4+ T cells they infect." (PMID 37873119, 2023). "The CD4 was only available for individuals with HIV/HCV co-infection and the overall median baseline CD4 count was 336 cells per μL (IQR 240–461)." (PMID 38128044, 2023). "Consistent with this, we also found HIV infection elevated the production of perforin in CD4+ T cells, and HIV/TB co-infection had more granzyme A secretion in CD4+ T cells than HIV infection and TB alone." (PMID 37483385, 2023). "This study aimed to determine the association of hepatitis B e-antigen (HBeAg), baseline HBsAg level, sPD-1 and CD4 + T cell with HBsAg decline in HIV/HBV coinfection after the initiation of cART." (PMID 37207191, 2023). "Of the three reported deaths of patients with Mpox and HIV co-infection, two cases had a CD4+ T-cells count < 200/μL." (PMID 36851124, 2023). "There was a significant decline in CD4 + T cell counts in such co‐infection groups (HIV + T. gondii, HIV + HCV + T. gondii, and HIV + HBV + HCV + T. gondii) compared with the HIV mono‐infection group." (PMID 36840494, 2023). "It has been shown that co-infection with HBV or HCV or with both of them can strongly decrease the CD4+ count, and the decline in CD4+ count is significantly higher in the triple co-infection (HIV/HBV/HCV) than in double co-infection (HIV/HBV or HIV/HCV)." (PMID 37942194, 2023). "The odds of syphilis co-infection were also higher in those with CD4 count <500 cells/mm3 (AOR (95%CI) = 2.5 (1.5–11.7)) and HAART-naive (AOR (95%CI = 3.1 (1.2–10.2)." (PMID 37498806, 2023). "These metabolites, though detected in an extremely small cohort, give an indication of which metabolic analyses would be most pertinent to investigating the effect of CD4 T-cell count in individuals with HIV/TB co-infection." (PMID 37592227, 2023). "After co-infection, CD4+ T cell IL-2 responses also dominated but peaked at 14 dpi (mean of 0.12%) and then declined over time." (PMID 37287962, 2023).
co-infection (continued). "A significant decline in CD4 cell counts was found in such co‐infection groups (HIV + T. gondii, HIV + HCV + T. gondii, and HIV + HBV + HCV + T. gondii) compared with the HIV mono‐infection group." (PMID 36840494, 2023). "Low CD4+ T cell count, smoking, and intravenous drug use were the primary risk factors for HIV/TB co-infection, whereas BCG vaccination history was a protective factor." (PMID 37674103, 2023). "In contrast, co-infection induced exclusively H3N2-specific single-cytokine producers CD4+ T cells (85% of IL-2, 8.8% of TNF, and 4% of IFN-γ)." (PMID 37287962, 2023). "Seventeen participants (89%) had HIV-coinfection, 16 of whom were receiving antiretroviral therapy and had a median CD4+ T cell count of 38 cells/μL and HIV viral load (VL) of 443 copies/mL at the time of sample collection." (PMID 37740179, 2023). "Studies using the NHP model of Mtb/SIV co-infection revealed protective CD4+ T cell-independent immune responses that suppress LTBI reactivation." (PMID 37764928, 2023). "Our study also observed that the CD4 cell count of TB/HIV coinfection cases was lower than that of both LTBI and HIV mono-infection patients among PLWH." (PMID 36231580, 2022). "An important marker of immune activation following Mtb/HIV coinfection in humans is elevated frequencies of HLA-DR+CD4+ T cells, reflecting chronic T cell activation." (PMID 34855621, 2022). "The median CD4 count at presentation in patients with HIV coinfection was 211 cells/μL (IQR 127-401 cells/μL)." (PMID 35869241, 2022). "The independent relevant elements for anemia were low CD4 count, females, and co-infection with PM, TB, or HCV." (PMID 36474196, 2022). "A bivariate analysis was done to determine the association between variables (age, gender, CD4 count, viral load, and HIV/HBV co-infection) using Chi square test." (PMID 36417469, 2022). "This directly supports evidence that HIV-infected individuals have shown a 2- to 3- fold increase in the transition to active TB within the first year of HIV coinfection when CD4+ T cells are still relatively abundant." (PMID 36405707, 2022). "The intersecting SARS-CoV-2, HIV, and TB epidemics pose additional concerns, particularly as T cell immunity and SARS-CoV-2–specific CD4+ T cells are reduced and display lower polyfunctional capacity in the setting of co-infection." (PMID 36846557, 2022). "Covariates for adjusted models included maternal HIV viral load, CD4 count, cytomegalovirus co‐infection, antiretroviral therapy exposure, gestational age at blood sampling and randomised trial arm." (PMID 35916394, 2022). "Patients with HCV/HIV co-infection showed significant differences between CD4+ T cell numbers and the viral subtype they carried." (PMID 35632686, 2022). "Different evidence confirmed that the recovery of CD4 + T-cells among patients who had HIV-TB co-infection was poor." (PMID 35284661, 2022). "In the present study, anaemia was associated with night sweats, a longer duration of fever, low BMI, hyperthermia, high sputum bacillary loads, HIV co-infection, and low CD4 and CD8 counts at bivariate analysis." (PMID 35022106, 2022). "This prevalence ranges from 4% to 11.43% with CD4 < 100 cells/mm3 as a common factor and sometimes co-infection with other diseases." (PMID 36547569, 2022). "Half of the patients were undergoing antiretroviral treatment at the time of coinfection diagnosis with a median CD4+ count of 350 cells/μL and a viral load of 1500 copies/μL." (PMID 36287507, 2022). "This study aims to analyze prevalence and risk factors associated with co-infection of hepatitis B virus (HBV) and/or hepatitis C virus (HCV) in HIV-positive patient besides their CD4+ T cells status." (PMID 35239716, 2022). "Our study showed that some demographic variables (age, gender, and education) and clinical variables (clinical stage, TB/HIV, and HBV/HIV coinfections) are associated with AHD and fewer CD4 cell counts in people with HIV from Southern Iran." (PMID 35846073, 2022).